CDCA5 (cell division cycle associated 5)
Diseases named in the same sentence as CDCA5 in open-access papers (continued):
Sharing a sentence is not in itself a finding about the gene and the disease.
colon cancer (2 papers, 2021 to 2024). "Real‐time PCR, cell clone formation assay, CCK-8 assay, cell proliferation assay, migration assay, invasion assay and apoptosis assay were used to evaluate the effect of CDCA5 silencing on colon cancer cell lines." (PMID 38213717, 2024). "Given that the COAD results were significant in multiple analyses and that the relationship between COAD and CDCA5 had not been investigated, we concentrated on colon cancer to verify the relationship between CDCD5 and tumors." (PMID 38213717, 2024).
liver cirrhosis (2 papers, 2024 to 2025). "In HCC, a four-gene combination involving KIF4A, UBE2T, CDCA3, and CDCA5 can track disease progression from chronic active hepatitis B (CAH-B) and liver cirrhosis (LC) to HCC." (PMID 41361459, 2025). "However, no study reported the role of CDCA5 in chronic active hepatitis B and liver cirrhosis." (PMID 38890649, 2024).
non-small cell lung carcinoma (2 papers, 2018 to 2022). A group of at least three distinct histological types of lung cancer, including non-small cell squamous cell carcinoma, adenocarcinoma, and large cell carcinoma. "A poor prognosis for non-small cell lung cancer was linked to CDCA5 overexpression." (PMID 29467944, 2018).
bladder (1 paper, 2020). "Therefore, our data first revealed that the CDCA5-mediated antiapoptotic pathway plays a pivotal role in bladder carcinogenesis." (PMID 32201512, 2020).
bladder tumor (1 paper, 2020). "Our results also showed that compared with matched peritumor tissues, bladder tumor tissues highly expressed CDCA5." (PMID 32201512, 2020).
cholangiocarcinoma (1 paper, 2024). A carcinoma that arises from the intrahepatic biliary tree (intrahepatic cholangiocarcinoma) or from the junction, or adjacent to the junction, of the right and left hepatic ducts (hilar cholangiocarcinoma). "Additionally, a differential expression analysis of these genes based on cholangiocarcinoma and normal tissues samples from the TCGA database revealed significant upregulation of CDCA5, FAM111B, MCM8 and PCNA in cholangiocarcinoma, supporting their relevance in this context." (PMID 38687509, 2024).
ductal carcinoma (1 paper, 2022). "Regarding histological tumor subtype, high CDCA5 mRNA expression was associated with ductal carcinoma of no special type (NST) compared to the special subtypes (p < 0.001)." (PMID 36428736, 2022).
esophageal adenocarcinoma (1 paper, 2024). A malignant tumor with glandular differentiation arising predominantly from Barrett mucosa in the lower third of the esophagus. "To determine if CDCA5 mutations affect the clinical outcomes of cancer patients, we found that CDCA5 alterations may be a risk factor for esophageal adenocarcinoma patients." (PMID 38213717, 2024).
gastric adenocarcinoma (1 paper, 2022). "Notably, the inhibition of CDCA2 and CDCA5 activities in lung and gastric adenocarcinoma, respectively, resulted in the downregulation of CCNE1 expression, thereby inhibiting cancer cell proliferation and blocking it in the G1 phase." (PMID 36004205, 2022).
glioma (1 paper, 2024). A benign or malignant brain and spinal cord tumor that arises from glial cells (astrocytes, oligodendrocytes, ependymal cells). "Combined with the GDSC drug database, CDCA2, CDCA4, CDCA5, CDCA7, and CDCA8 have potential as clinical drug treatments for glioma." (PMID 38181024, 2024). "And subsequent multivariate COX regression analyses suggested that CDCA2, CDCA5, and CDCA8 were independent prognostic factors for glioma." (PMID 38181024, 2024). "CDCA2, CDCA4, CDCA5, CDCA7, and CDCA8 showed high accuracy for diagnosing gliomas, with CDCA7 having the highest accuracy (AUC: 0.982)." (PMID 38181024, 2024). "CDCA2, CDCA3, CDCA4, CDCA5, CDCA7, and CDCA8 were significantly highly expressed in glioma samples." (PMID 38181024, 2024).
Hyperglycemia (1 paper, 2023). An increased concentration of glucose in the blood. "According to our data, hyperglycemia alone caused upregulation of a number of genes such as TGFA, CDCA5, MUC3A and C3AR1." (PMID 37511575, 2023).
malignant glioma (1 paper, 2020). A grade III or grade IV glioma arising from the central nervous system. "CDCA5 is also a biomarker of malignant glioma of neural stem cell origin." (PMID 32528520, 2020).
nasopharyngeal carcinoma (1 paper, 2021). A carcinoma arising from the nasopharyngeal epithelium. "Another example of a multi-layered regulation was recently described for CDCA5/Sororin in nasopharyngeal carcinoma (NPC) and hepatocellular carcinoma (HCC)." (PMID 34707078, 2021).
triple-negative breast carcinoma (1 paper, 2022). An invasive breast carcinoma which is negative for expression of estrogen receptor (ER), progesterone receptor (PR), and human epidermal growth factor receptor 2 (HER2). "It was to explore the effect of cell division cycle associated 5 (CDCA5) under shRNA interference on proliferation and metastasis of triple negative breast cancer (TNBC) cells." (PMID 35726220, 2022).
urinary bladder urothelial carcinoma (1 paper, 2018). "In another study, CDCA5 overexpression was linked to G1-S transition malfunction in urinary bladder urothelial carcinoma." (PMID 29467944, 2018).
uterine diseases (1 paper, 2020). "Conditional loss of EZH2 in the uterus upregulated genes associated with uterine diseases, including keratin 5 (Krt5), keratin 15 (Krt15), the maternally-imprinted gene- H19, leucine-rich repeat-containing G-protein-coupled receptor 5 (Lgr5), and cell division cycle associated 5 (Cdca5)." (PMID 33732505, 2020).
uterine papillary serous carcinoma (1 paper, 2020). "As to uterine serous carcinoma/uterine papillary serous carcinoma, the most common alterations were the high mRNA expression of all CDCA members, the amplification of CDCA5, CBX2 and CDCA8 and the missense mutation of CDCA2/7." (PMID 32913454, 2020).
tumor (52 papers, 2008 to 2025). "According to the Mann-Whitney U and Spearman correlation analysis, expression of CDCA5 was significantly associated with tumor size and T infiltrate (p < 0.05)." (PMID 38978058, 2024). "In our work, we analyzed CDCA5 expression, survival status, DNA promoter methylation, mutations in genes, alternative splicing, immunological infiltration, tumor immune single cells, and enrichment." (PMID 38213717, 2024). "Another research found that increased CDCA5 expression was associated with increased tumor diameter and microvascular invasion in HCC." (PMID 34143800, 2021). "The present study found that increased CDCA5 expression was associated with increased tumor diameter and microvascular invasion in HCC." (PMID 30497429, 2018). "We categorized CDCA5 expression as high or low by the median value of positive rate of tumor cells, and then examined the association between CDCA5 expression and the clinicopathological parameters of the OSCC patients." (PMID 26497678, 2016). "Additionally, a clinical correlation analysis was performed to establish the association between CDCA5 mRNA expression and tumor pathological stages." (PMID 38213717, 2024). "Given that tumor microenvironment is tightly associated with tumor progression and therapy, and ccRCC is a type of classical immune-infiltrated tumor, we propose that CDCA5-mTOR may also participate tumor immunity and this is deserved to be determined." (PMID 38658931, 2024). "The current study indicates that there is a significant association between high CDCA5 and aggressive tumor features including larger tumor size, high tumor grade, LVI positivity, hormonal receptor negativity, HER2 positivity and independent prognostic factor for worse patient outcomes." (PMID 36428736, 2022). "Accumulating studies showed that increased CDCA5 level was a diagnostic biomarker and risk factor for numerous cancers which could enhance the tumor cells' capability of proliferation and metastasis by oncogenic ERK5-AP-1 pathway." (PMID 32149105, 2020). "However, underlying mechanism of CDCA5 knockdown on suppression tumor growth of CRC cells need to be explored in future studies." (PMID 30808873, 2019). "The aberrant expression of CDCA5 in tumor tissue may be caused by a high degree of DNA methylation." (PMID 37287817, 2023). "The identification of CDCA5 is also consistent with recent work highlighting its contribution to tumor growth via the ERK pathway." (PMID 41446353, 2025). "The clinical correlation analysis included various tumor types from TCGA, revealing significant differences in CDCA5 mRNA expression between KICH, KIRC, KIRP, LIHC, LUAD, LUSC, BRCA and their respective normal matched tissues (P<0.05)." (PMID 38213717, 2024). "The results demonstrated that CDCA5 KD group showed a significantly reduced tumor growth, compared to the NC group." (PMID 38658931, 2024). "Silencing of CDCA5 resulted in significant induction of tumor cell apoptosis, in line with increased activity of Caspase3/7." (PMID 38658931, 2024). "Compared with normal tissues, CDCA5 is upregulated in various tumor types, such as in KIRC with statistical significance." (PMID 38658931, 2024). "Previous research has demonstrated that downregulation of CDCA5 suppresses several tumor growth 7-10." (PMID 38213717, 2024). "In this study, through data-mining across TCGA database and tumor tissues detection, we found that CDCA5 expression is upregulated in ccRCC." (PMID 38658931, 2024). "This inhibited, either partially or fully, the expression of the CDCA5 protein, thereby inhibiting tumor cell proliferation and promoting apoptosis." (PMID 37847340, 2024). "Statistics verified the significant difference of CDCA5 overexpression in tumor tissues (50.0%) and normal tissues (31.8%) (p < 0.001)." (PMID 38978058, 2024).
tumor (continued). "We next evaluated the essential role of FOXM1 in CDCA5-induced tumor growth in vivo by subcutaneous injection of CDCA5-overexpressed, FOXM1-depleted, CDCA5-overexpressed + FOXM1-depleted or NC MDA-MB-231 cells." (PMID 38978058, 2024). "Recent studies have highlighted the significant role of CDCA5 in tumorigenesis and tumor progression." (PMID 38658931, 2024). "Elevated CDCA5 expression is associated with an increase in immune cell infiltration in KIRC, COAD and THCA, which suggests that CDCA5 is closely related to tumor TME." (PMID 38213717, 2024). "We examine the DNA methylation level of CDCA5 in tumor and normal tissue in light of its aberrant expression pattern." (PMID 37287817, 2023). "We noticed an aberrant expression level between tumor and normal tissue in most cancer, indicating that CDCA5 has a potent cancer-related effect." (PMID 37287817, 2023). "The strong association with cadherins, TGF-β1 and LVI positivity strengthens our in vitro findings, highlighting the importance of CDCA5 in BC tumor progression and further supports its role in promoting the migratory and invasive mechanisms." (PMID 36428736, 2022). "Our findings emphasize the significance of CDCA5 expression and its role in cell migration and evading apoptosis in BC tumor progression and worse patients’ clinical outcome." (PMID 36428736, 2022). "shRNA interference technology can knock down the expression of CDCA5 and inhibit its “tumor promotion” effect." (PMID 35726220, 2022). "CDCA5 plays important roles in migration, proliferation, apoptosis, and invasion of tumor cells by regulating sister chromatid segregation and cohesion." (PMID 33778011, 2021). "Regarding PAAD, increased CDCA expression along with advanced PAAD tumor stage, NUF2, CDCA2, CDCA3, CDCA4 and CDCA5 expression are risk factors for poor prognosis, while CBX2 expression is a protective factor (P < 0.05)." (PMID 33437202, 2021). "By analyzing the differentially expressed genes between CDCA5-low and -high HCC tumor samples, we found that genes involved in cell cycle were significantly enriched in CDCA5-high tumors." (PMID 32694239, 2020). "Acting as a regulator of sister chromatid cohesion in cell-cycle, CDCA5 exhibit the pro-tumor ability by regulating proliferation process of tumor cells." (PMID 32694239, 2020). "Using the GEPIA database, the present study also revealed that CDCA5 expression was significantly higher in tumor tissues than in matched normal tissues among various tumors." (PMID 32201512, 2020). "In our work, we used tissue microarrays (TMA) to evaluate the histopathological features of CDCA5 in HCC tumor samples and analyze the survival outcomes of 304 HCC tumor samples based on CDCA5 expression." (PMID 32694239, 2020). "We next analyzed the protein expression of CDCAs and the result indicated low protein expression of CDCA5/6/8 in normal tissues and high protein expression in tumor tissues." (PMID 32716971, 2020). "Meanwhile, further validation by GEO datasets also demonstrated the higher CDCA5 expression in tumor tissues." (PMID 32694239, 2020). "Knockdown of CDCA5 inhibits the tumor growth of BCa cells in vivo.To further confirm the effect of CDCA5 on BC growth in vivo, we injected sh-NC and sh-CDCA5-1 T24 cells subcutaneously into the flanks of NOD-SCID mice to establish a xenograft tumor model." (PMID 32201512, 2020). "By identifying significant miRNAs potentially regulated by CDCA5 expression, we found that hsa-mir-144, a tumor suppressor miRNA in various cancer types including HCC, was significantly up-regulated in CDCA5-high patients." (PMID 32694239, 2020). "Consistent with previous studies on various tumor types, higher expression of CDCA5 was found in HCC tumor cells than in adjacent normal tissues." (PMID 32694239, 2020).
tumor (continued). "In conclusion, our study provided the evidence of CDCA5 as an oncogenic promoter in HCC and the potential function of CDCA5 in affecting tumor microenvironment." (PMID 32694239, 2020). "Silencing CDCA5 expression suppressed the tumor growth in vitro and in vivo, possibly by inhibiting the ERK signaling." (PMID 30808873, 2019). "This was also the first study demonstrating that CDCA5 expression was directly correlated with tumor diameter." (PMID 30497429, 2018). "The objective of this study was to confirm the prognostic value of CDCA5 expression levels in HCC and to shed light on tumor characteristics associated with CDCA5 expression." (PMID 30497429, 2018). "On the 30th day after injection, the tumor weights in the control group and the CDCA5 low expression group were 0.89 ± 0.07 and 0.66 ± 0.11 g, respectively." (PMID 30497429, 2018). "Patients with CDCA5 overexpression had larger tumor diameters and a higher incidence of microvascular invasion compared with patients with decreased CDCA5 expression." (PMID 30497429, 2018). "The median tumor diameter in the high CDCA5 expression group was 6.67 ± 3.97 versus 5.11 ± 2.42 in the low CDCA5 expression group (P = 0.006)." (PMID 30497429, 2018). "CDCA5 expression was significantly decreased in the tumor tissue from the CDCA5 low expression group compared with that from the HepG2 group (P < 0.05)." (PMID 30497429, 2018). "The expression of CDCA5 mRNA in tumor and adjacent normal tissue derived from the same patient was examined by qRT-PCR." (PMID 26497678, 2016). "The KEGG data indicates that “DNA replication” and “cell cycle” may have a role in the influence of CDCA5 on tumor pathogenesis." (PMID 38213717, 2024). "The previous findings have proved that mTOR is essential for CDCA5 function in ccRCC, we thus examine whether the pro-tumor function of CDCA5/EEF1A1 was via mTOR pathway." (PMID 38658931, 2024). "In addition, mTOR and CDCA5 has been extensively reported to regulate immune cell function and activity as well as tumor immunity." (PMID 38658931, 2024). "Our study speculated that endogenous CDCA5 may enhance the probability of tumor oncogenesis in the examined cell lines." (PMID 36428736, 2022). "Thus, studies found that TNBC cell proliferation, migration, and tumor were inhibited by RNA interference with CDCA5." (PMID 35726220, 2022). "In accordance with this study findings, high CDCA5 expression may contribute to tumor proliferation via regulating cyclin E1 expression." (PMID 36428736, 2022). "In the METABRIC cohort, high CDCA5 mRNA expression demonstrated a significant correlation with well-established poor prognosis characteristics including larger tumor size, high histological grade, nodal status-positivity, LVI-positivity, ER & PR negativity, and HER2-positivity (p < 0.001)." (PMID 36428736, 2022). "Based on our observation, high CDCA5 expression may contribute to suppressing the cell adhesion process by facilitating BC tumor cell migration through the lymphatic vessels and by invasion through activating the Wnt and PI3K signalling pathways." (PMID 36428736, 2022). "Among the top 100 genes that have similar expression patterns of KIFC1 in the tumors of the TCGA cohort, the KIFC1 expression was significantly and positively correlated with KIF2C, NCAPH, KIF4A, TPX2, and CDCA5 expression in all of the tumor types in the TCGA database." (PMID 35327439, 2022). "Results: this study examined cohorts showed that high CDCA5 expression was correlated with features characteristic of aggressive behavior and poor prognosis, including the presence of high grade, large tumor size, lymphovascular invasion (LVI), hormone receptor negativity and HER2 positivity." (PMID 36428736, 2022). "Finally, overexpression of TPI1 increased expression of N-cadherin, vimentin, LDHA, p-mTOR, and CDCA5, whereas reduced E-cadherin in tumor tissues as demonstrated by WB." (PMID 35509067, 2022).